TRAP1 (TNF receptor associated protein 1)
Diseases named in the same sentence as TRAP1 in open-access papers (continued):
Sharing a sentence is not in itself a finding about the gene and the disease.
colorectal adenocarcinoma (2 papers, 2017 to 2023). The most common type of colorectal carcinoma. "Our study showed that TRAP1 was associated with local invasion in colorectal adenocarcinomas." (PMID 28088229, 2017). "In conclusion, we clarified the relationship between TRAP1 expression and clinicopathologic factors, and evaluated diagnostic and prognostic significance of TRAP1 as a potential biomarker, using a large number of human colorectal adenocarcinoma FFPE samples." (PMID 28088229, 2017). "In colorectal adenocarcinomas, high-TRAP1 expression was observed in 564 patients (79%) and 150 patients (21%) showed low-TRAP1 expression." (PMID 28088229, 2017). "Our results firmly indicated that TRAP1 was as a novel independent prognostic factor for colorectal adenocarcinomas." (PMID 28088229, 2017). "Our multivariate analysis showed that TRAP1 expression was useful for predicting the clinical outcome of colorectal adenocarcinomas." (PMID 28088229, 2017). "Therefore, TRAP1 expression can be used as an additional novel prognostic marker of colorectal adenocarcinomas." (PMID 28088229, 2017). "Multivariate analysis indicated that TRAP1 expression (hazard ratio, 1.947; 95% CI, 1.270 to 2.984; p = 0.002), and pathologic T stage (hazard ratio, 3.190; 95% CI, 1.275 to 7.983; p = 0.013) were independent prognostic factors for colorectal adenocarcinomas." (PMID 28088229, 2017). "Cox proportional hazard regression analysis indicated that TRAP1 expression (hazard ratio, 1.947; 95% CI, 1.270 to 2.984; p = 0.002), and pathologic T stage (hazard ratio, 3.190; 95% CI, 1.275 to 7.983; p = 0.013) were independent prognostic factors for colorectal adenocarcinomas." (PMID 28088229, 2017).
diabetes (2 papers, 2020 to 2024). "Histological analysis showed that diabetes-induced glycogen accumulation and structural damage were prevented by TRAP1 overproduction." (PMID 32215175, 2020). "First, this study showed that TRAP1 significantly ameliorates diabetes-induced renal injury, and this protection may be correlated with its antiapoptotic effects on renal tubular cells." (PMID 32215175, 2020). "Thus, our results suggest that TRAP1 ameliorates diabetes-induced renal injury by preventing abnormal mPTP opening and maintaining mitochondrial structure and function, which may be treated as a potential target for DKD treatment." (PMID 32215175, 2020). "Furthermore, retinal thickness, indicative of retinal neurodegeneration in diabetes, was decreased in Trap1+/+, but not in Trap1−/−, STZ mice." (PMID 37983591, 2024).
esophageal cancer (2 papers, 2017 to 2021). A primary or metastatic malignant neoplasm involving the esophagus. "The aim of this study was to investigate the anticancer effects of shikonin on esophageal cancer (EC) cells and explore the underlying molecular mechanism by identifying dysregulation in shikonin-induced tumor necrosis factor receptor-associated protein 1 (TRAP1) expression." (PMID 34812264, 2021).
leukemia (2 papers, 2021 to 2023). A malignant (clonal) hematologic disorder, involving hematopoietic stem cells and characterized by the presence of primitive or atypical myeloid or lymphoid cells in the bone marrow and the blood. "To do this, we searched our proteomics dataset for mitochondrial proteins with known kinase and/or ATPase function that were substantially upregulated across all three leukemia lines and identified mitochondrial TRAP1." (PMID 34132194, 2021). "In the context of cancer cells, mtHsp90, specifically TRAP1, has the potential to function as either a proto-oncogene or an oncogene, though it is commonly observed to be overexpressed in various cancer types, including prostate, breast, lung, and leukemia." (PMID 38098505, 2023). "Although prior work has identified TRAP1 as a potential anticancer target in leukemia, genetic knockdown in MV-4–11 cells increased, rather than decreased, cellular proliferation in the present study." (PMID 34132194, 2021). "TRAP1 is the mitochondrial paralog of the heat shock protein 90 (HSP90) family and is widely recognized as a potential anticancer drug target across multiple human malignancies, including leukemia." (PMID 34132194, 2021).
malignant peripheral nerve sheath tumor (2 papers, 2021 to 2022). Malignant peripheral nerve sheath tumor (MPNST) is a rare and often aggressive soft tissue sarcoma occurring in a wide range of anatomical sites. "These molecules specifically inhibit TRAP1 ATPase activity with minimal effects on HSP90 and were found to inhibit in vitro growth of malignant peripheral nerve sheath tumor (MPNST) cells." (PMID 35883436, 2022).
metastatic disease (2 papers, 2017 to 2020). "High TRAP1 levels have been proposed as prognostic biomarker in this malignancy, being associated with extensive lymph node dissemination and, together with high ERCC1, with poor overall survival (OS) in metastatic disease." (PMID 28177905, 2017). "We have previously demonstrated that the expression of the molecular chaperone TRAP1 in HGSOC inversely correlates with stage, grade, and progression to metastatic disease and directly correlates with survival." (PMID 32235572, 2020).
metastatic prostate carcinoma (2 papers, 2011 to 2012). A carcinoma that arises from the prostate gland and has spread to other anatomic sites. "TRAP1/Hsp75 (tumor necrosis factor receptor associated protein 1), a paralogue of the Hsp90 family, has been recently described as a molecular marker and novel therapeutic target in local and metastatic prostate cancer." (PMID 22978347, 2012). "This is consistent with the abundant distribution of one of the targets of Gamitrinibs, the mitochondrial Hsp90 homologue TNF receptor-associated protein-1, in all Gleason grade localised and metastatic prostate cancer in humans, but not benign prostatic hyperplasia." (PMID 21285984, 2011).
oral squamous cell carcinoma (2 papers, 2021 to 2022). "One data showed that TRAP1, an important regulatory molecule for glucose metabolism in CAFs, was able to promote oral squamous cell carcinoma progression by regulating OXPHOS in CAFs." (PMID 36246404, 2022).
pancreatic cancer (2 papers, 2021 to 2026). "Histochemical investigations of SDH activity on tissue slices showed that SDH activity was strongly reduced in tumor masses compared to the normal pancreas, and incubation with the specific TRAP1 inhibitor compound 5 restored the SDH enzymatic activity in samples of pancreatic tumors." (PMID 33934112, 2021).
sarcoma (2 papers, 2025). A usually aggressive malignant neoplasm of the soft tissue or bone. "In keeping with this, TRAP1 point mutations affect the growth and migration of aggressive sarcoma cells, and alter sensitivity to a selective TRAP1 inhibitor." (PMID 40074754, 2025). "Accordingly, only a faint re-expression of the human T600P TRAP1 (hTRAP1-T600P) could be obtained in murine sarcoma cells where the endogenous TRAP1 had been knocked out, while a significant increase in protein expression occurred upon proteasome inhibition." (PMID 40074754, 2025). "In cancer cells, the TRAP1 C261S/C573R mutant is unable to inhibit the activity of its client succinate dehydrogenase and to confer protection against oxidative insults, thus hampering the invasiveness of aggressive sarcoma cells." (PMID 40424720, 2025).
ulcerative colitis (2 papers, 2015 to 2017). An inflammatory bowel disease involving the mucosal surface of the large intestine and rectum. "This evidence is consistent with previous studies showing that TRAP1 is upregulated in both dysplastic and non-dysplastic tissues of ulcerative colitis progressors, being its levels lower in colon tissues from ulcerative colitis non-progressors." (PMID 28177905, 2017).
Acidosis (1 paper, 2021). Abnormal acid accumulation or depletion of base. "Our study showed that, in extracellular acidosis, MIC60 protein was degraded by a ubiquitin-proteasome system (UPS) dependent way, and TRAP1 could increase MIC60 protein levels by inhibiting MIC60 ubiquitination." (PMID 34907169, 2021).
acute lymphoblastic leukemia (1 paper, 2017). Leukemia with an acute onset, characterized by the presence of lymphoblasts in the bone marrow and the peripheral blood. "Bioinformatics analysis of public databases revealed that TRAP1 was prominently upregulated in pediatric AML patients, compared to normal bone marrow, or B- or T-cell Acute Lymphoblastic Leukemia (ALL)." (PMID 29348817, 2017).
Anxiety (1 paper, 2017). Intense feelings of nervousness, tension, or panic often arise in response to interpersonal stresses. "However, the clinical correlation of the variants present in those subjects (TRAP1 p.Ile253Val in subject ECS031 and CACNA1A p.Ser2423_Gly2424del in subject ECS100) with migraine and anxiety is uncertain." (PMID 29145497, 2017).
atherosclerosis (1 paper, 2024). A disease characterized by the build-up of fatty material and calcium deposition in the arterial wall resulting in partial or complete occlusion of the arterial lumen. "Recent research indicates that elevated tumour necrosis factor receptor-associated protein 1 (TRAP1) expression reprograms energy metabolism, leading to senescence and atherosclerosis (AS) in vascular smooth muscle cells (VSMCs)." (PMID 39325940, 2024). "TRAP1 intensifies atherosclerosis by promoting the transcriptional activation of the H4K12la phenotype associated with senescence in smooth muscle cells." (PMID 39325940, 2024).
B-cell non-Hodgkin lymphoma (1 paper, 2022). The most common type of non-Hodgkin lymphoma. "Here we assessed the surface and intracellular expression of constitutive cytosolic HSP90β isoform, mitochondrial HSP90 homolog TRAP1 and co-chaperone STIP1/HOP in T, NK, B and NKT cells derived from peripheral blood and bone marrow samples of patients with Hodgkin and B-cell Non-Hodgkin lymphomas." (PMID 35572591, 2022).
cardiac hypertrophy (1 paper, 2020). "Overexpression of TRAP1 has been shown to protect against pressure overload-induced cardiac hypertrophy." (PMID 32982788, 2020). "Overexpression of TRAP1 elicits protection against cardiac hypertrophy by improving mitochondrial function, presumably by maintaining mitochondrial proteostasis." (PMID 32982788, 2020).
dysplasia (1 paper, 2022). A usually neoplastic transformation of the cell, associated with altered architectural tissue patterns. "Additionally, TRAP1-negative mice have signs of diminished lifespan, with abnormal tissue generation, dysplasia, and cells delivered from such mice with impaired cell proliferation were non-viable, thus suggesting that TRAP1 inhibitors have potential as senolytic agents." (PMID 35054835, 2022).
familial Mediterranean fever (1 paper, 2024). Familial Mediterranean fever (FMF) is an autoinflammatory disorder characterized by recurrent short episodes of fever and serositis resulting in pain in the abdomen, chest, joints and muscles. "Recently, three related subjects with homozygous mutations for MEFV p.S208C and TRAP1 p.R128H presented with familial Mediterranean fever (FMF) with no reported opportunistic infection." (PMID 39224595, 2024).
glomerulonephritis (1 paper, 2018). A renal disorder characterized by damage in the glomeruli. "Overexpression of TRAP1 in glomerulonephritis was accompanied by DNaseI shutdown, which happens in end-stage disease, suggesting transcriptional interference between TRAP1 and DNaseI genes." (PMID 30158430, 2018).
Huntington disease (1 paper, 2025). Huntington disease (HD) is a rare neurodegenerative disorder of the central nervous system characterized by unwanted choreatic movements, behavioral and psychiatric disturbances and dementia. "A site‐selective approach targeting the Hsp90 N‐terminal binding pocket, specifically for cytosolic isoforms α and β over Grp94 and TRAP‐1, has been emphasized in Huntington's disease (HD)." (PMID 40293270, 2025).
Immunodeficiency (1 paper, 2024). Failure of the immune system to protect the body adequately from infection, due to the absence or insufficiency of some component process or substance. "Extending from TRAP1, mutations in other HSPs may potentially lead to immunodeficiency." (PMID 39224595, 2024).
lung squamous cell carcinoma (1 paper, 2021). "The mRNA expression levels of TRAP1 and HSPD1 were increased in lung squamous cell carcinoma." (PMID 34712697, 2021).
lymphocytopenia (1 paper, 2024). "In conclusion, our study provides novel insights into TRAP1 mutations associated with CD4+ lymphocytopenia and PjP susceptibility." (PMID 39224595, 2024). "Taken together, our study uncovered a previously unrecognized role of TRAP1 in CD4+ lymphocytopenia, conferring susceptibility to opportunistic infections." (PMID 39224595, 2024). "Through a case of idiopathic CD4+ lymphopenia, we uncovered a previously unrecognized role of the mitochondrial chaperon protein Tumour Necrosis Factor-Receptor Associated Protein 1 (TRAP1) in CD4+ lymphocytopenia and in the mechanism of PjP immunopathogenesis." (PMID 39224595, 2024). "Further investigations may be warranted to explore the precise mechanism by which TRAP1 dysregulation caused lymphocytopenia and inflammasome activation." (PMID 39224595, 2024). "The increased apoptotic markers found in patient PBMCs in the presence of idiopathic CD4+ lymphocytopenia suggest that CD4+ T cells are especially sensitive to TRAP1 dysfunction." (PMID 39224595, 2024).
lymphoma (1 paper, 2022). A malignant (clonal) proliferation of B- lymphocytes or T- lymphocytes which involves the lymph nodes, bone marrow and/or extranodal sites. "Since lymphoma originates from lymphocytes we sought to analyze the expression of HSP90β, TRAP1 and STIP1 co-chaperone in peripheral blood and bone marrow lymphocytes of patients with Hodgkin and Non-Hodgkin lymphomas." (PMID 35572591, 2022). "HSP90β and STIP1 were overexpressed in B lymphocytes, while TRAP1 expression was decreased in T, B, NK and NKT cells of lymphoma patients." (PMID 35572591, 2022).
major depression (1 paper, 2012). "Although TRAP1 has various functions we have shown that TRAP1 mediates TNF-alpha/TNF receptor 1 signaling to modulate N-cadherin expression and to regulate cell adhesion and synaptic morphology, which may be involved in the pathogenesis of major depression." (PMID 23284813, 2012).
migraine (1 paper, 2017). "Two of the subjects with migraine headaches harbor variants in other genes that have previously been associated with migraine (TRAP1 and CACNA1A)." (PMID 29145497, 2017).
myocardial ischemia (1 paper, 2021). A disorder of cardiac function caused by insufficient blood flow to the muscle tissue of the heart. "In addition, TRAP1 is reported to convey its anti-apoptotic properties through an abrogation of ROS production as demonstrated by Zhang and colleagues in a myocardial ischemia model and through its ability to reduce ER stress." (PMID 34769067, 2021).
nephritis (1 paper, 2023). Inflammation of renal tissue. "In the other mouse line with a Dnase1 mutation without affecting Trap1, a rather mild increase of autoantibodies and nephritis score is reported from 9 months onwards." (PMID 36969253, 2023).
neurofibromatosis (1 paper, 2022). A hereditary neoplastic syndrome in which tumors grow in the nervous system. "Taken together, these data suggest that TRAP1 inhibition or combined TRAP1-Erk1/2 targeting may be a viable therapeutic strategy in neurofibromatosis and other cancers." (PMID 35740911, 2022).
Opportunistic infection (1 paper, 2024). An infection that is caused by a pathogen that would generally not be able to cause an infection in a host with a normal immune system. "Our study elucidates the role of TRAP1 through E93Q/A64T which compromises mitochondrial function, particularly during infection and stress, resulting in susceptibility to opportunistic infections." (PMID 39224595, 2024). "This revealed that a chaperon, the mitochondrial paralog of HSP90, TRAP1, may have been involved in the patient’s susceptibility to an opportunistic infection." (PMID 39224595, 2024).
osteoarthritis (1 paper, 2023). A noninflammatory degenerative joint disease occurring chiefly in older persons, characterized by degeneration of the articular cartilage, hypertrophy of bone at the margins and changes in the synovial membrane. "Our previous study has confirmed that miR338-3p/TRAP-1 axis was involved in regulation of hyperactivation in human synovial fibroblasts (HFLS) of patients with osteoarthritis (OA)." (PMID 37920489, 2023).
ovarian tumor (1 paper, 2012). "TRAP1, described to be involved in apoptosis evasion, was observed to be significantly up-regulated in Cisplatin resistant ovarian tumor cell lines." (PMID 22978347, 2012).
pancreatic adenocarcinoma (1 paper, 2021). "TRAP1 expression, which was very low in fish pancreas under physiological conditions, was strongly increased both at protein and mRNA levels in K-RasG12D-driven pancreatic adenocarcinomas." (PMID 33934112, 2021). "In order to confirm these in silico predictions, we exposed to hypoxia both Zebrafish embryos and human pancreatic adenocarcinoma MIA PaCa-2 cells, finding an increase of TRAP1 mRNA levels." (PMID 33934112, 2021).
rectum adenocarcinoma (1 paper, 2019). An adenocarcinoma arising from the rectum. "The clinical significance of TRAP1 CN was explored in TCGA colon and rectum adenocarcinoma (COADREAD) database." (PMID 31878280, 2019).
renal agenesis (1 paper, 2024). Renal agenesis (RA) is a form of renal tract malformation characterized by the complete absence of development of one or both kidneys (unilateral RA or bilateral RA respectively), accompanied by absent ureter(s). "TNF receptor-associated protein 1 (TRAP1), in particular, encodes a heat-shock protein 90-related mitochondrial chaperone that is involved predominantly in the development of the proximal tubules leading to renal agenesis in patients with autosomal recessive mutations of TRAP1." (PMID 39791075, 2024).
Salmonella Infections (1 paper, 2016). Infections with bacteria of the genus SALMONELLA. "Both TRAP1 and AXIN 1, the two putative candidate genes on chromosome 14 for Campylobacter colonisation resistance, have been also associated with Salmonella infection in previous studies." (PMID 27090510, 2016).
small cell lung carcinoma (1 paper, 2010). Small cell lung cancer (SCLC) is a highly aggressive malignant neoplasm, accounting for 10-15% of lung cancer cases, characterized byrapid growth, and early metastasis. "Trap1 and Grp94 are therefore candidate alternate targets for the effects of Hsp90 inhibitors on small cell lung cancer cells both on the basis of their known affinities for Hsp90 inhibitors and their established roles in the prevention of cell death." (PMID 20552022, 2010). "The cell death seen in small cell lung cancer cells is therefore due to inhibition of a target other than cytosolic Hsp90; likely alternate targets include either the endoplasmic reticulum Hsp90 paralog Grp94 or the mitochondrial Hsp90 paralog Trap1." (PMID 20552022, 2010). "If, as our data suggests, the apoptotic effect of Hsp90 inhibitors in small cell lung cancer is due to inhibition of other Hsp90 family members, such as Grp94 or Trap1, it will be important to develop new drugs that are optimized for selectivity and potency for these targets." (PMID 20552022, 2010).
Stroke (1 paper, 2021). Sudden impairment of blood flow to a part of the brain due to occlusion or rupture of an artery to the brain. "Moreover, overexpression of TRAP1 in rats decreased infarct volumes after experimental stroke and improved their post-ischemic neurobehavioral score." (PMID 34769067, 2021).